PUS7 (pseudouridine synthase 7)
Diseases named in the same sentence as PUS7 in open-access papers (continued):
Sharing a sentence is not in itself a finding about the gene and the disease.
tumor (25 papers, 2017 to 2026). "Elucidating the mechanisms underlying PUS7 downregulation in certain cancers may offer new insights into tumor heterogeneity and inform precision therapeutic strategies." (PMID 40940790, 2025). "Flow cytometry and immunofluorescence analysis of tumour tissues further revealed that DNase I administration significantly reduced M2 macrophages while increasing M1 macrophages in PUS7‐overexpressing tumours." (PMID 41496500, 2026). "Specifically, PUS7 overexpression induced a shift towards the M2 macrophage phenotype, which is widely recognized for its immunosuppressive and tumour‐promoting properties." (PMID 41496500, 2026). "To further elucidate the relationship between PUS family gene expression and tumour behaviour, we validated the mRNA and protein levels of PUS7 in PDAC." (PMID 41496500, 2026). "Effective depletion of neutrophils markedly attenuated the accelerated tumour growth induced by PUS7 overexpression." (PMID 41496500, 2026). "Strikingly, exposure to NETs‐containing supernatant derived from PUS7‐overexpressing tumour cells robustly induced M2‐like macrophage polarization, as evidenced by a significantly increased CD206/CD86 ratio." (PMID 41496500, 2026). "Western blot analysis of paired tumour and adjacent normal tissues from 12 PDAC patients further confirmed significantly increased PUS7 protein levels in tumour samples." (PMID 41496500, 2026). "RNA sequencing analysis of tumour cells revealed that PUS7 overexpression significantly altered the expression of multiple cytokines and chemokines implicated in neutrophil recruitment and activation." (PMID 41496500, 2026). "PUS7‐depleted cells exhibited significantly reduced volume and weight compared with controls, while PUS7‐overexpressing tumours showed markedly accelerated growth." (PMID 41496500, 2026). "Future investigations should aim to integrate transcriptomic and proteomic analyses to assess the broader impact of PUS7 on cell signaling within the tumor microenvironment, offering insights into its role in tumor heterogeneity and resistance to therapy." (PMID 41554761, 2026). "Among them, PUS7 and PUS3 showed the strongest correlations with tumour‐promoting phenotypes, with high PUS7 expression in PDAC predicting poor overall survival." (PMID 41496500, 2026). "This was evidenced in vivo by immunofluorescence, which showed upregulated levels of key NETs markers (MPO and CitH3) in PUS7‐overexpressing tumours." (PMID 41496500, 2026). "Together, these results showed that PUS7 silencing inhibits and its overexpression promotes tumour growth both in vitro and in vivo." (PMID 41496500, 2026). "Treatment with DNase I, an enzyme that degrades extracellular DNA, completely abolished the tumour‐promoting effect of PUS7 overexpression, indicating that NETs clearance alleviates PUS7‐driven tumour growth." (PMID 41496500, 2026). "IHC staining confirmed significantly higher PUS7 expression in tumour tissues compared with adjacent non‐tumourous pancreatic tissues (ANT)." (PMID 41496500, 2026). "PUS7, a pseudouridine synthase, modulates pseudouridylation levels in tumour cells and influences the Akt kinase (AKT) signalling pathway, which suppresses apoptosis." (PMID 39834094, 2025). "PUS7 plays a critical role in promoting tumor growth and progression in multiple in vivo cancer models." (PMID 40940790, 2025). "Collectively, these in vivo studies demonstrate that PUS7 is a critical driver of tumor growth and progression across diverse cancer types, highlighting its potential as a therapeutic target in oncology." (PMID 40940790, 2025). "DKC1 enhances ribosomal protein expression to promote cancer progression; PUS7 improves the proliferation and invasion of tumor cells." (PMID 41446042, 2025). "Inhibition of PUS7 has been shown to impair tumor cell proliferation and stress adaptation, making it an attractive candidate for novel epitranscriptomic-based therapies." (PMID 40940790, 2025).
tumor (continued). "As the oncogenes of CRC, both nuclear enriched abundant transcript 1 (NEAT1) and Pseudouridine synthase 7 (PUS7) are involved in the initiation of the tumor through SIRT1/Wnt/β-catenin axis in the nude mice model." (PMID 40567502, 2025). "Together, these findings underscore PUS7 as a key oncogenic regulator that promotes tumor progression by modulating multiple signaling pathways." (PMID 40940790, 2025). "PUS7 plays an important role in this process because it directly catalyzes this pseudouridinylation, and PUS7 has been recently identified as a promising prognostic marker in tumor diseases themselves." (PMID 40699665, 2025). "PUS7 contributes to tumor progression by modulating key cellular processes such as the cell cycle and apoptosis." (PMID 40940790, 2025). "Several studies have shown that PUS7 contributes to tumor progression by modulating key oncogenic signaling pathways." (PMID 40940790, 2025). "In selected tumor entities, two important new central target structures, PUS7 and WTAP, were identified that directly control essential points for proliferation, which was impressively supported by annotation clustering." (PMID 40699665, 2025). "Most notably, PUS7 was aberrantly expressed in 20 tumor types (83%), with 75% of the tumors exhibiting upregulated PUS7 expression." (PMID 39162904, 2024). "Macroscopically subcutaneous tumours of PUS7‐depleted MKN45 cells were robustly diminished by exogenous expression of ALKBH3 or PUS7." (PMID 39175405, 2024). "Research indicates that NSCLC patients with high PUS7 expression in tumor tissues experience a markedly reduced survival rate." (PMID 39737343, 2024). "PUS7 expression in tumor tissues was detected by immunohistochemical staining, and we evaluated the influence of PUS7 expression on the prognosis of NSCLC patients after surgery using Cox regression analysis, both univariate and multivariate." (PMID 37420297, 2023). "Our study shows that PUS7 expression in tumor tissue is an independent prognostic factor for NSCLC patients, and the OS of NSCLC patients with high expression of PUS7 in tumor tissue is significantly shorter." (PMID 37420297, 2023). "Univariate analysis showed that gender, PUS7 expression, tumor pathological type, adjuvant chemotherapy, and clinical stage were prognostic factors (P all < 0.05)." (PMID 37420297, 2023). "The application of PUS7 inhibitors inhibited tumorigenesis and prolonged the life span of tumor-bearing mice." (PMID 36437949, 2022). "NMS-E973 showed increased anti-tumour metastasis activity when combined with PUS7 suppression in CRC." (PMID 33990203, 2021). "The PUS7-KD DLD1 tumours treated with NMS-E973 showed the lowest number of metastatic nodules in contrast to that in the control group." (PMID 33990203, 2021). "Next, to assess the effect of PUS7 inhibition combined with NMS-E973 on tumour metastasis in vivo, we injected DLD1-shPUS7 and DLD1-shNC cells into the tail vein of BABL/c nude mice." (PMID 33990203, 2021). "PUS7 at 7q22.3 was amplified in 3 G3 tumours and lost in 7 G1 tumours (Fisher’s exact p-value: 0.0050343)." (PMID 28486536, 2017). "Our findings suggest that targeting PUS7 or downstream NETs formation may represent a viable approach to alleviate immunosuppression and restrain tumour progression." (PMID 41496500, 2026). "Direct inhibition of PUS7 represents an upstream strategy that may simultaneously affect tumour‐intrinsic programs and tumour–immune interactions." (PMID 41496500, 2026). "PUS7 overexpression markedly increased tumour burden compared with controls." (PMID 41496500, 2026). "Consistently, analysis of the tumour immune microenvironment revealed that neutrophil depletion significantly reduced the accumulation of M2‐polarized macrophages in PUS7‐overexpressing tumours, while partially restoring macrophage polarization towards a less immunosuppressive phenotype." (PMID 41496500, 2026).
tumor (continued). "Our data indicate that NETs degradation selectively abrogates PUS7‐driven tumour growth and M2 macrophage polarization, suggesting that NETs inhibition may be particularly effective in tumours with high PUS7 activity." (PMID 41496500, 2026). "Importantly, administration of the NETs inhibitor DNase I markedly reversed PUS7‐induced M2 polarization in orthotopic mouse models and significantly suppressed tumour growth in vivo, which suggests that NETs serve as a key mediator in the PUS7‐TAM axis." (PMID 41496500, 2026). "Notably, several soluble factors associated with NET induction, including CXCL2, CXCL8, and IL‐6, were markedly upregulated in PUS7‐overexpressing tumour cells compared with controls." (PMID 41496500, 2026). "Therefore, PDAC was selected as a focused model to investigate the potential role of PUS7 in coordinating RNA modification–dependent immune remodelling within the tumour microenvironment." (PMID 41496500, 2026). "To determine whether PUS7 promotes PDAC progression through NETs, we established an orthotopic tumour model by implanting Pan02 cells stably overexpressing PUS7 (Pan02‐PUS7) into C57BL/6 mice." (PMID 41496500, 2026). "The results suggest that PUS family members, including PUS1, RPUSD1, RPUSD3, and PUS7, may contribute to both enhanced tumour stemness and the establishment of an immunosuppressive microenvironment in PAAD." (PMID 41496500, 2026). "To directly determine whether NETs function as the essential intermediate linking PUS7‐overexpressing tumour cells to macrophage phenotypic reprogramming, we established an in vitro Transwell‐based sequential co‐culture system." (PMID 41496500, 2026). "Our findings indicate that PUS7 functions upstream of NETs formation, and that pharmacological degradation of NETs via DNase I abolishes the tumour‐promoting effects of PUS7 in orthotopic mouse models, thereby validating the functional significance of this pathway." (PMID 41496500, 2026). "DKC1 promotes tumor spread, invasion, and migration; PUS7 promotes cell growth and self-renewal." (PMID 41446042, 2025). "Furthermore, the context-dependent nature of PUS7 activity complicates the prediction of therapeutic responses across different tissues or tumor types." (PMID 40940790, 2025). "Furthermore, comparative analyses also identified further putative target mRNAs of importance for tumor biology of PUS7 and WTAP." (PMID 40699665, 2025). "In addition, DKC1 and PUS7 expression were negatively correlated with DSS time in nine of the tumor types." (PMID 39162904, 2024). "Furthermore, PUS7 attenuates tumor growth by modifying the U696 site with pseudouridine, thereby increasing the translation efficiency of the ALKBH3 mRNA." (PMID 39737343, 2024). "PUS7 overexpression promotes tRNA pseudouridylation, promoting tumor cell growth and self-renewal." (PMID 39737343, 2024). "PUS7 expression affected the PFI in more than 10 tumor types." (PMID 39162904, 2024). "PUS7 has been shown to have oncogenic functions in some tumours." (PMID 39175405, 2024). "In addition, they detected chemical inhibitors of PUS7 that inhibited PUS7-mediated Ψ modifications, suppressed tumorigenesis, and prolonged the lifespan of tumor-bearing mice." (PMID 37007137, 2023). "PUS7 can promote the progression of NSCLC, and the higher expression of PUS7 in tumor tissue indicates poor prognosis of patients, which may be a biomolecule that affects prognosis." (PMID 37420297, 2023). "We obtained pathological specimens from NSCLC patients in the First Affiliated Hospital, Sun Yat-sen University, and then performed immunohistochemical staining to evaluate the correlation between PUS7 and patient prognosis based on the expression of PUS7 in tumor tissues." (PMID 37420297, 2023). "Altogether, our data suggest that PUS7 promotes tumour metastasis via LASP1 in CRC cells." (PMID 33990203, 2021).
tumor (continued). "To rationalize the vital role of PUS7 in OV, we explored the proteins interacting with PUS7, which may partially help explain PUS7 function in tumor diagnosis, tumorigenesis, and development." (PMID 34827123, 2021). "Altogether, these results suggest that PUS7 overexpression promotes tumour metastasis in vivo." (PMID 33990203, 2021). "Similarly, high PUS7 positive staining was significantly linked to T classification, and high LASP1 positive staining was significantly linked to tumour size, T classification, and clinical stage." (PMID 33990203, 2021). "Therefore, HSP90 suppressors are promising combination partners in the context of PUS7 blockade agents for the treatment of PUS7-overexpressing tumours." (PMID 33990203, 2021). "Additionally, it remains unclear whether the PUS7‐NETs‐macrophage axis is conserved across other tumour types." (PMID 41496500, 2026). "Therefore, targeting the PUS7–NETs axis may sensitize PDAC tumours to standard‐of‐care chemotherapy or potentially enhance the efficacy of immunotherapies by restoring macrophage polarization and improving immune infiltration." (PMID 41496500, 2026). "However, a subset of cancer types exhibits reduced PUS7 expression, which may result from tissue-specific regulatory mechanisms or reflect context-dependent roles, including a potential tumor-suppressive function." (PMID 40940790, 2025). "Additionally, combining PUS7 inhibition with agents targeting mRNA translation or epigenetic modifiers could synergistically impair tumor growth by disrupting layered regulatory networks." (PMID 40940790, 2025). "In addition, the significance of PUS7 has also been observed in other tumor studies." (PMID 37420297, 2023). "Similar to RPUSD3, the expression of PUS7 may also imply higher tumor purity." (PMID 36437949, 2022). "Hence, the mechanistic comprehension of the HSP90/PUS7/LASP1 axis in CRC metastasis will open novel research opportunities for the elucidation of the functional consequences of PUS7 in the context of tumour development and for the development of new treatment approaches for CRC." (PMID 33990203, 2021). "Here, we identify a novel function of PUS7 in PDAC, expanding its oncogenic potential beyond intrinsic tumour cell behaviour to include modulation of the tumour immune microenvironment." (PMID 41496500, 2026). "We found that PUS7 reshapes the PDAC immune landscape primarily by inducing NETs, which drive macrophage polarization from M1 to M2, fostering immune suppression and tumour progression." (PMID 41496500, 2026). "To further analyze the regulatory role of PUS7 within TME and its interaction with NETs, we performed single‐cell RNA sequencing on orthotopic PDAC tumours after adenovirus injection." (PMID 41496500, 2026). "PUS7 reshapes the PDAC immune landscape primarily by inducing NETs, which drive macrophage polarization from M1 to M2, fostering immune suppression and tumour progression." (PMID 41496500, 2026). "Various PUSs, including PUS7, PUS1, and DKC1, have been shown to regulate tumorigenesis by modulating tumor cell proliferation and apoptosis." (PMID 40260225, 2025). "We found that PUS1, PUS7, and PUS10 maintained consistent copy number amplification in most tumor types." (PMID 39162904, 2024). "Previous studies have also shown that PUS7 and DCK1 regulation of MYC expression promotes tumor malignancy." (PMID 37925171, 2023). "Studies have found PUS7 is highly expressed in GBM and predicts poor survival, moreover, PUS7 inhibitors can efficiently suppress GSC-derived tumor progression." (PMID 36923941, 2023). "Increasing evidences have suggested an association between abnormal expression of Ψ synthases (such as PUS1, PUS7, PUS10 and DKC1) and tumor malignant progression." (PMID 35118063, 2021).
tumor (continued). "In contrast to its potent effects in the PUS7‐overexpressing setting, DNase I treatment did not significantly alter tumour volume or macrophage polarization status in Vector control tumours, nor did it cause significant body weight loss." (PMID 41496500, 2026). "Moreover, tumours from DNase I‐treated PUS7‐overexpressing mice exhibited decreased levels of the NETs markers MPO and CitH3, confirming that DNase I suppresses PUS7‐induced NETs formation in vivo." (PMID 41496500, 2026). "Collectively, these findings suggest that PUS7 overexpression may promote NETs formation in PDAC, which may, in turn, contribute to enhanced tumour progression." (PMID 41496500, 2026). "For instance, PUS7 enhances translation of ATF4, a central ISR transcription factor, thereby promoting cellular adaptation to amino acid deprivation and endoplasmic reticulum stress conditions encountered in the MYCN-driven tumor microenvironment." (PMID 40940790, 2025). "Additionally, PUS7 enhances the translation efficiency of ALKBH3 mRNA by modifying the U696 site with pseudouridine, thereby attenuating tumour growth." (PMID 39175405, 2024). "As for the apoptosis of tumor cells, the results of flow cytometry indicated that neither knockdown nor overexpression of PUS7 affected the apoptosis level of NSCLC cells (P all > 0.05)." (PMID 37420297, 2023). "We initially calculated the univariate and multivariate analysis of overall survival (OS) rate, including the expression of genes belonging to the PUS family (PUS1, PUS3, PUS7, PUS10, PUS7L, PUSL1), patients’ age, gender, race and Tumor Node Metastasis (TNM)-stage, and set grade as co-variate." (PMID 37315299, 2023). "In the GSE59612 dataset, the expression of PUS1, PUS7, RPUSD1 and DKC1 were significantly increased in the tumor core tissues relative to tumor marginal tissues and paracancerous tissues; and the expression of TRUB1 was decreased from paracancerous tissue to tumor core tissue." (PMID 35118063, 2021). "We then explored the median expression of PUS7 mRNA across all tumour samples and matched non-malignant tissues using the GEPIA website." (PMID 33990203, 2021). "Moreover, PUS7 has been reported to modify MALAT1, a tumour-related and well-studied long non-coding RNA." (PMID 33990203, 2021). "Furthermore, individual members such as PUS7 in GBM suppress T‐cell recruitment by reducing chemokine expression, promoting immune evasion, while PUS1 in HCC stabilizes proliferation‐related mRNAs, accelerating tumour growth." (PMID 41496500, 2026). "The most affected tumor type was PRAD, in which the expression of five synthases, DKC1, PUS3, RPUSD4, PUS7, and TRUB2, had mostly negative effects on DSS." (PMID 39162904, 2024). "In addition, IHC analysis of a cohort of 56 pairs of CRC specimens (tumour and matched non-malignant tissues) collected from the Xijing Hospital of Digestive Diseases was performed to verify that LASP1 was overexpressed in CRC tissues and positively linked to PUS7." (PMID 33990203, 2021).